ELOA3DP (elongin A3 family member D, pseudogene)
Synonyms: ELOA3D; ELOA3L2; TCEB3CL2
Gene: Processed pseudogene on chromosome 18 (46,962,768 to 46,964,408, reverse strand). Ensembl gene ENSG00000288616.
Genetic constraint (gnomAD): Missense variants: 0 observed, 0.8 expected, observed/expected ratio (o/e) 0, 90% interval 0 to 1.77. Synonymous variants: 0 observed, 0.78 expected, observed/expected ratio (o/e) 0, 90% interval 0 to 1.78.